LRRC14 (leucine rich repeat containing 14)
Description:
Negatively regulates Toll-like receptor-mediated NF-kappa-B signaling by disrupting IKK core complex formation through interaction with IKBKB.
Synonyms: KIAA0014; LRRC14A
Tractability: PROTAC: ubiquitination databases record sites on it; its protein half-life has been measured.
Gene: Protein-coding gene on chromosome 8 (144,517,965 to 144,525,178, forward strand). Ensembl gene ENSG00000160959.
Subcellular location: Cytoplasm
Subcellular location (Human Protein Atlas): Cytosol; Nucleoplasm
Pathways (Reactome):
Immune System: Regulation of NF-kappa B signaling
Gene Ontology:
Molecular function: kinase binding; protein binding
Biological process: negative regulation of toll-like receptor signaling pathway
Cellular component: cytoplasm; cytosol
Genetic constraint (gnomAD): Loss-of-function variants: 17 observed, 24.44 expected, observed/expected ratio (o/e) 0.7, 90% interval 0.47 to 1.04. The synonymous counts are far from expectation, so gnomAD's model fits this gene poorly and the ratio says little. Missense variants: 575 observed, 625.01 expected, observed/expected ratio (o/e) 0.92, 90% interval 0.86 to 0.99. Synonymous variants: 344 observed, 281.85 expected, observed/expected ratio (o/e) 1.22, 90% interval 1.12 to 1.33.
Homologues: Orthologues: chimpanzee LRRC14 (100% identical), pig LRRC14 (97% identical), dog LRRC14 (96% identical), guinea pig LRRC14 (95% identical), mouse Lrrc14 (94% identical), macaque MFSD3 (93% identical), rat Lrrc14 (93% identical), tropical clawed frog lrrc14 (49% identical), zebrafish si:ch73-174h16.4 (33% identical). Paralogues in human: LRRC14B (30% identical), PRAMEF6 (29% identical), PRAMEF25 (28% identical), PRAMEF26 (28% identical), PRAMEF27 (28% identical), PRAMEF5 (28% identical), PRAMEF9 (28% identical), PRAME (28% identical), PRAMEF11 (28% identical), PRAMEF15 (28% identical), PRAMEF4 (28% identical), PRAMEF20 (27% identical), and 12 more.
Diseases named in the same sentence as LRRC14 in open-access papers:
LRRC14 is named in the same sentence as 2 diseases in open-access papers, as found by Europe PMC text mining. Sharing a sentence is not in itself a finding about the gene and the disease. The quoted sentences say what the papers report.
glaucoma (1 paper, 2025). Increased pressure in the eyeball due to obstruction of the outflow of aqueous humor. "Additionally, PPI network analysis showed that IRF1, IFI30, NR3C1 and LRRC14 have relatively abundant interacting proteins, suggesting that these genes might act as key regulatory nodes in the molecular pathways underlying HBP and glaucoma." (PMID 41170525, 2025). "The number of interacting proteins for IRF1, IFI30, NR3C1 and LRRC14 was relatively abundant, suggesting that they may play a key role in the regulatory pathways of HBP and glaucoma." (PMID 41170525, 2025).
LRRC14 also shares sentences with these, for which no sentence is quoted: tumour (1 paper).